RELN (reelin)
Diseases named in the same sentence as RELN in open-access papers (continued):
Sharing a sentence is not in itself a finding about the gene and the disease.
autism spectrum disorder (27 papers, 2013 to 2023). A spectrum of developmental disorders that includes autism, and Asperger syndrome. "Reelin plays a pivotal role in neurodevelopment and in post-natal synaptic plasticity and has been implicated in the pathogenesis of autism spectrum disorder (ASD)." (PMID 27134686, 2016). "Several lines of evidence from multiple studies now implicate heterozygous mutations in RELN in autism spectrum disorders (ASD)." (PMID 27064498, 2016). "Additionally, change in RELN which decrease the production of reelin has been associated with autism spectrum disorder and other neurodevelopmental disorders (Folsom & Fatemi, 2013; Ishii, Kubo, & Nakajima, 2016)." (PMID 32596987, 2020). "Researchers have found that rs362691 was not only associated with autism spectrum disorders (ASDs) but might also take part in the influence of the RELN gene on the cognitive functions of healthy people." (PMID 30891068, 2019). "A reduced blood level of reelin is a vulnerability factor in the pathophysiology of autistic spectrum disorders." (PMID 38137152, 2023). "Genetic alterations in RELN have been variably reported as possible contributors to the pathogenesis of autism spectrum disorders (ASD)." (PMID 35422848, 2022). "Autistic spectrum disorder (ASD) is a complex neurodevelopmental disability with a genetic basis, and several studies have suggested a potential role of the reelin gene (RELN) in ASD susceptibility." (PMID 33143244, 2020). "Additional research will be needed to elucidate the mechanism of FGFRs in Reelin-induced migration and spine density and the link with autism spectrum disorders." (PMID 31577229, 2019). "Genetic and epigenetic changes in components of the Reelin-signaling pathway (RELN, DAB1) are associated with autism spectrum disorder (ASD) risk." (PMID 27184477, 2016). "As we excluded all children with suspected autism spectrum disorder, we can infer that changes in RELN have broader effects than just deficits in social interaction and communication, but may also affect general learning structures and functions." (PMID 32596987, 2020). "Moreover, a reduced reelin expression has been observed in several brain regions of subjects with Autism Spectrum Disorders." (PMID 23700474, 2013). "In addition, a significant enrichment among the nominal DEGs for genes implicated in autism spectrum disorder (ASD) was found (e.g., AFF2, DNER, DPP6, DPP10, RELN, CACNA1C), as well as several that are strong candidate genes for the development of eye problems found in LS, including glaucoma." (PMID 32393163, 2020).
breast carcinoma (22 papers, 2012 to 2025). "We found that α3β1 represses the expression of Reelin, a secreted glycoprotein that inhibits invasion and for which loss of expression is associated with poor prognosis in breast cancer." (PMID 33477804, 2021). "We also show that increased Reelin expression following RNAi-mediated suppression of α3β1 causes a significant decrease in breast cancer cell invasion." (PMID 33477804, 2021). "Because loss of Reelin has been associated with decreased survival of breast cancer patients, we sought to determine the effects of α3β1-mediated silencing of Reelin on breast cancer cell invasion." (PMID 33477804, 2021). "Loss of RELN expression has indeed been shown to induce cell migration in esophageal carcinoma, and to be associated with poor prognosis in breast cancer." (PMID 30838036, 2019). "We found that protein-altering mutations in RELN are associated with increased tumor PI in each breast cancer subtype, and that low levels of RELN expression are associated with poor prognosis within the basal subtype." (PMID 28454104, 2017). "For example, RELN was among the top 5 genes in breast cancer ranked by protein altering mutations associated with increased PI values in each subtype." (PMID 28454104, 2017). "In gastric, pancreatic, and breast cancer, the decrease of reelin was associated with tumoral proliferation and increased invasivity." (PMID 28255385, 2017). "Focusing on breast cancer, the largest cancer cohort available, we found one relatively less investigated gene, RELN, among the top PI associated genes." (PMID 28454104, 2017). "In breast cancer, the loss of reelin expression in tumor cells is associated with tumor proliferation." (PMID 28255385, 2017). "We also examined survival advantage in breast cancer patients (n=3554) and found that high expression of RELN was associated with a better relapse-free survival." (PMID 27071537, 2016). "Recently, several groups reported that loss of functional Reelin was implicated in motility and invasion of pancreatic, gastric, and breast cancer." (PMID 22393371, 2012). "Although reduced Reelin expression in breast cancer has been associated with hypermethylation of the RELN gene, disease progression, and decreased survival, mechanisms through which the RELN gene is regulated in breast cancer remain unknown." (PMID 33477804, 2021). "In breast cancer, reduced RELN expression is associated with increased invasion and poor prognosis." (PMID 33477804, 2021). "Moreover, low RELN expression in breast cancer is associated with increased cancer cell migration, positive lymph node status, and poor prognosis." (PMID 33477804, 2021). "The idea that reelin may function outside of the CNS and PNS has been supported by recent works that have linked the reelin signaling pathway to different cancers, such as prostate, gastric, and breast cancers." (PMID 34205192, 2021). "Breast cancer patients within the basal-like subtype tended to have shorter survival times if their tumors harbored protein altering mutations or were low expressers of RELN compared to patients with tumors expressing RELN at high levels (p = 0.08)." (PMID 28454104, 2017). "Furthermore, loss of Reelin correlates with decreased survival of lung and breast cancer patients." (PMID 27071537, 2016). "The expression of RELN decreased in breast cancer, colorectal cancer and pancreatic cancer, but increased in retinoblastoma, myeloma and prostate cancer." (PMID 40171042, 2025). "Simultaneously, the differentially expressed genes related to breast cancer, such as FHL1, GPM6B, RELN, and CXCL10 were discovered between the two risk groups." (PMID 38748500, 2024). "Reduced reelin expression is associated with increased DNMT-1 in gastric and breast cancers, and a gradual increase in DNMT-1 mRNA abundance from ulcerative colitis to colitis-associated colorectal tumors has been reported." (PMID 36290310, 2022).
breast carcinoma (continued). "Our findings demonstrate a critical role for α3β1 in promoting cell invasion through repression of Reelin, highlighting the potential value of this integrin as a therapeutic target for breast cancer." (PMID 33477804, 2021). "Our current findings demonstrate that integrin α3β1 significantly represses the expression of Reelin, a secreted glycoprotein that is known to be repressed or silenced in breast cancer." (PMID 33477804, 2021). "Overall, our study identifies an important role for α3β1-dependent regulation of RELN that impacts breast cancer cell invasion, highlighting the potential clinical importance of exploiting integrin α3β1 as a therapeutic target for breast cancer." (PMID 33477804, 2021). "Based on the GEO database, we found that Reelin was significantly upregulated in CAFs compared with TCs in breast cancer, pancreatic cancer, and rectal carcinoma." (PMID 34485127, 2021). "The current study identifies a novel role for integrin α3β1 in repressing Reelin expression, adding to a number of other important functions that this integrin plays in promoting breast cancer." (PMID 33477804, 2021). "Various studies have since shown that the RELN gene is epigenetically silenced in breast cancer, as well as in other cancers such as gastric and pancreatic cancer." (PMID 33477804, 2021). "Our findings demonstrate a critical role for Reelin in breast cancer cell invasion, as increasing Reelin expression in Reelin-low cells decreased invasion, while decreasing Reelin expression in Reelin-high cells increased invasion." (PMID 33477804, 2021). "Specifically, the expression of Reelin is reduced in hepatocellular carcinoma, gastric carcinoma, colorectal cancer, glioblastoma, breast cancer, and pancreatic cancers." (PMID 34485127, 2021). "RELN is epigenetically repressed in breast cancer, and low RELN expression correlates with increased cancer cell migration and poor prognosis." (PMID 33477804, 2021). "In breast cancer, pancreatic cancer and rectal cancer, Reelin in CAFs was significantly upregulated compared with Reelin in TCs." (PMID 34485127, 2021). "In human breast cancer biopsies, Reelin is expressed in adjacent, normal breast epithelium, but it is absent from cancerous tissue." (PMID 33477804, 2021). "In this study we demonstrate that α3β1 represses RELN expression to enhance breast cancer cell invasion." (PMID 33477804, 2021). "Again, this advantage was even higher for patients with grade 1 disease histology, with hazard ratio between high and low RELN expression of 0.71 for all breast carcinoma and 0.53 for grade 1 disease." (PMID 27071537, 2016). "The physiological function of Reelin was intensively studied in brain, however, recently, RELN was found to be epigenetically silenced in different cancers including pancreatic, gastric and breast cancer." (PMID 22393371, 2012). "Reelin, another protein important in neuronal migration in the brain, was recently shown to be epigenetically silenced in breast cancer compared with normal mammary tissue." (PMID 22375924, 2012). "Indeed, it was found that brain-tropic breast cancer cells produce more reelin compared to their parental counterparts." (PMID 37728789, 2023). "RELN is epigenetically repressed or silenced in breast cancer." (PMID 33477804, 2021). "Moreover, in breast cancer, a previous study showed that enhanced Reelin in MDA-MB231 cells suppressed invasiveness of cancer cells in vitro." (PMID 34485127, 2021). "Overall, these results indicate that the enhanced expression and secretion of Reelin that occurs in α3-KD cells contributes to the reduced invasive potential of these cells, supporting a model wherein integrin α3β1 represses Reelin expression to promote breast cancer cell invasion." (PMID 33477804, 2021). "Moreover, several studies have now shown that Reelin expression is reduced in many cancers, including breast cancer." (PMID 33477804, 2021).
breast carcinoma (continued). "Therefore, it is noteworthy that our current study identifies a role for α3β1 in the down-regulation of the RELN gene, as Reelin is an extracellular protein that inhibits breast cancer cell invasion." (PMID 33477804, 2021). "Interestingly, Reelin is differentially expressed within different breast cancer subtypes; Her2-positive breast tumors were found to express higher levels of Reelin compared to TNBC tumors and metastases." (PMID 33477804, 2021). "Future studies to investigate the mechanisms through which α3β1 represses RELN gene expression should offer new insights into therapeutic strategies to block this regulation in breast cancer cells and promote up-regulation of anti-invasive proteins such as Reelin." (PMID 33477804, 2021). "Our findings indicate there may be intriguing roles for RELN in the progression of breast cancer particularly related to tumor proliferation; however, future functional investigations are necessary to confirm its role." (PMID 28454104, 2017). "Finally, we found that both lung adenocarcinoma and breast carcinoma patients have better survival expectancy when Reelin levels in their tumours were higher." (PMID 27071537, 2016). "In parallel studies for downregulated genes, we were able to identify seven genes with mutations in colon cancer (DPP10, PCSK2, ADAM33, RELN, CAPN13, ADAMTS1 and ADAMTS15), and five genes with mutations in breast carcinomas (MASP3, ABHD12B, TLL1, CPA3 and DPP6)." (PMID 24243807, 2013). "The relationship between reelin and estrogen/breast cancer is not fully understood." (PMID 22905152, 2012). "Therefore, we next wanted to determine whether genetic modulation of RELN expression alters the invasive properties of breast cancer cells." (PMID 33477804, 2021). "However, low-expressed Reelin significantly correlated with poor clinical outcome in breast cancer." (PMID 34485127, 2021). "Furthermore, dormant brain-tropic breast cancer sublines of MDA-MB-231 and BT474 overexpress reelin after co-culture with neurons." (PMID 37728789, 2023). "However, a role for integrins in the regulation of Reelin expression has not been previously explored in breast cancer cells." (PMID 33477804, 2021).
Anxiety (15 papers, 2015 to 2025). Intense feelings of nervousness, tension, or panic often arise in response to interpersonal stresses. "In open field test wild-type, heterozygous and homozygous mutants for reelin spent a similar amount of time in the side and center of the tank, indicating that reelin homozygous exploration, anxiety behavior and aggression altered." (PMID 33671313, 2021). "In the future, it would be interesting to extend the behavioral work to assess other aspects of memory, motivation, reward and anxiety, and to compare the effects of Reelin with those of antiepileptic, anxiolytic, and antipsychotic drugs." (PMID 33615226, 2021). "Reelin overexpression in a transgenic mouse model showed an anxiety-reducing, anti-depressant effect, as well as a reduction in psychotic and autistic behaviors." (PMID 34490028, 2021). "Microinjections of recombinant Reelin protein into the hippocampus rescued impairments in object memory and anxiety-like behavior and recruited synaptoporin in the hippocampus in offspring exposed to antenatal inflammation." (PMID 32982694, 2020). "Therefore, our results suggest that HFE acts as an inhibitor of DNA methylation, especially Reelin methylation, to restore hippocampal function, anxiety, and cognitive function by increasing hippocampal function-related gene transcription." (PMID 39339187, 2024). "Wild-type and reelinΔ28–/– mutants have similar measurements for anxiety indicating anxiety behavior is not affected by reelin mutation." (PMID 33262688, 2020). "However, deletion of the positively charged carboxy-terminal region of RELN attenuates canonical RELN signaling and leads to decreased social interaction, impaired working memory, hyperactivity and decreased anxiety compared to WT." (PMID 31607872, 2019). "Therefore, many problems currently muddy the picture, and need to be solved before our understanding of Reelin’s function in regulating anxiety-like behavior is clear." (PMID 27346785, 2016). "Among them, hyperactivity and ASD-like symptoms are likely to derive from developmental or anatomical defects while reduced anxiety-like behavior is from reduced Reelin functions in adult brain, since only the latter was observed in adult-specific Reelin KO mice." (PMID 27346785, 2016). "In rats, prenatal restraint stress decreased Reelin expression in the brain, possibly by affecting the DNA methylation levels of the Reelin promoter, and induced excessive spontaneous locomotor activity, increased anxiety-like behavior, and learning and memory deficits." (PMID 27346785, 2016). "Conversely, the cKO line exhibits slightly reduced anxiety levels when tested in the open field paradigm, a trait they share with reeler animals and is probably related to the roles of reelin in the adult brain rather than to developmental defects." (PMID 28747874, 2017).
psychosis (15 papers, 2015 to 2025). "Several lines of evidence obtained from such research suggest that the RELN gene, encoding reelin, is epigenetically altered in patients with psychosis, resulting in reduced expression of reelin." (PMID 26453695, 2015). "TNIK is up-regulated by either Apoer2-ICD, which provides another mechanism by which reduced Reelin signaling could impart risk for psychosis." (PMID 37461529, 2023). "This investigation into RELN DNAm in various phases of psychosis will allow an understanding of RELN dysregulation and its involvement in the development of psychosis." (PMID 36216926, 2022). "With more future experiments and on larger cohorts, there may be potential use of DNAm of the RELN gene as one of the genes for the biological-based marker for symptom severity in psychosis." (PMID 36216926, 2022). "Human post-mortem studies show that RELN is downregulated in GABAergic neurons of psychotic patients due to promoter hypermethylation of RELN gene that is associated with an increase in DNMT1 and DNMT3a which is consistent with the “epigenetic GABAergic theory of major psychosis”." (PMID 28670349, 2017). "It is unlikely from our locomotor hyperactivity data that HRM showed enhanced sensitisation of subcortical dopamine release following chronic Meth treatment and, by extension, these data do not support a role of reelin in the development of psychosis." (PMID 32580454, 2020). "Moreover, similar to what we have observed with PNNs, a previous study on the expression of reelin, an extracellular matrix protein, reported a downregulation in psychotic bipolar and schizophrenic patients when compared to control individuals and bipolar patients without psychosis." (PMID 31728775, 2019).